KRTAP22-2 (keratin associated protein 22-2)
Description:
In the hair cortex, hair keratin intermediate filaments are embedded in an interfilamentous matrix, consisting of hair keratin-associated proteins (KRTAP), which are essential for the formation of a rigid and resistant hair shaft through their extensive disulfide bond cross-linking with abundant cysteine residues of hair keratins. The matrix proteins include the high-sulfur and high-glycine-tyrosine keratins (By similarity).
Synonyms: KAP22.2
Tractability: No criterion of Open Targets' tractability assessment is met for any kind of drug.
Gene: Protein-coding gene on chromosome 21 (30,590,105 to 30,590,397, reverse strand). Ensembl gene ENSG00000206106.
Genetic constraint (gnomAD): Loss-of-function variants: 0 observed, 0.24 expected, observed/expected ratio (o/e) 0, 90% interval 0 to 1.87. That is too few expected variants to judge how well the gene tolerates losing a copy. Missense variants: 52 observed, 53.68 expected, observed/expected ratio (o/e) 0.97, 90% interval 0.77 to 1.22. Synonymous variants: 19 observed, 22.54 expected, observed/expected ratio (o/e) 0.84, 90% interval 0.59 to 1.24.
Homologues: Orthologues: chimpanzee KRTAP22-2 (100% identical).